CTSZ (cathepsin Z)
Diseases named in the same sentence as CTSZ in open-access papers (continued):
Sharing a sentence is not in itself a finding about the gene and the disease.
metastatic tumors (3 papers, 2015 to 2023). "The site of CTSZ mRNA expression is fundamental to determine its final role as a protective determinant in PCa, such as CTSZ mRNA in the blood cells, or a malignant determinant, such as found for CTSZ expressed in high levels by different types of primary and metastatic tumors." (PMID 34378678, 2021).
osteoporosis (3 papers, 2019 to 2025). A condition of reduced bone mass, with decreased cortical thickness and a decrease in the number and size of the trabeculae of cancellous bone (but normal chemical composition), resulting in increased fracture incidence. "ROC analysis showed that cathepsin Z mRNA has strong diagnostic value for osteoporosis and osteoporotic fracture." (PMID 31278293, 2019). "In the present experiments, it is shown that levels of cathepsin Z mRNA in clinical samples of peripheral blood mononuclear cells are significantly associated with osteoporosis, low bone mineral density and occurrence of fragility fractures." (PMID 31278293, 2019). "Importantly, cathepsin Z mRNA was significantly associated with fragility fracture in osteoporosis patients (P = 0.0018)." (PMID 31278293, 2019). "The diagnostic value of cathepsin Z mRNA in the osteoporosis patients that had experienced a previous fracture was even stronger than for the entire osteoporosis group (AUC, 0.96; sensitivity 100%, 95% CI 73.5 to 100%; specificity, 94.1%, 95% CI 71.3 to 99.9%)." (PMID 31278293, 2019). "The results show for the first time that cathepsin Z could be a future diagnostic biomarker for osteoporosis including female osteoporosis patients over the age of 50 years." (PMID 31278293, 2019). "Since these cell lineages produce the protease, cathepsin Z, the aim of this study was to investigate whether altered cathepsin Z mRNA levels are associated with osteoporosis in clinical samples." (PMID 31278293, 2019). "Thus, the presence of elevated levels of cathepsin Z mRNA/protein in the PBMC cells of osteoporosis patients, might be associated with altered behaviour of monocytes and T lymphocytes." (PMID 31278293, 2019). "That cathepsin Z is found in both osteoblast and osteoclast lineages of cells, the two cell types predominantly dysregulated in osteoporosis, raises the possibility that the occurrence of osteoporosis in human subjects might be associated with changes in cathepsin Z expression in these cells." (PMID 31278293, 2019). "That the PBMC preparations consist predominantly of immune cells raises the possibility that the observed osteoporosis-related increase in cathepsin Z mRNA reflects a change in the immune state of the osteopenia/osteoporosis patients relative to the normal controls." (PMID 31278293, 2019). "However, the increase in cathepsin Z mRNA level in osteopenia/osteoporosis was also observed when male and female participants over the age of 50, or female participants over the age of 50 were analysed." (PMID 31278293, 2019). "Thus, an increase in cathepsin Z mRNA in patients’ PBMCs was associated with reduced bone density using three clinical measures, lumbar and femoral T-score and BMD and with fracture in osteoporosis patients." (PMID 31278293, 2019). "However, for the osteoporosis group of patients, those patients with previous fractures exhibited levels of cathepsin Z mRNA that were highly significantly higher than for those without previous fractures (95% CI −0.529 to −0.126, P = 0.0018, post-hoc Bonferroni correction)." (PMID 31278293, 2019). "Elevated levels of cathepsin Z are found in osteopenia and osteoporosis and in diabetes, but there is no literature on cathepsin Z in diabetes bone disease." (PMID 41373586, 2025). "Cathepsin Z mRNA has been shown for the first time to be significantly elevated in the PBMCs of patients with either osteopenia or osteoporosis compared to non-osteoporotic controls." (PMID 31278293, 2019). "The results suggest that neither chronic inflammatory disorders nor chronic viral infections account for the observed increase in cathepsin Z mRNA levels in the osteopenia/osteoporosis patients compared to non-osteoporotic controls." (PMID 31278293, 2019).
osteoporosis (continued). "Irrespective of the biological effects of cathepsin Z, it has now been shown for the first time here that the increase in cathepsin Z mRNA in isolated PBMC fractions is very strongly diagnostic for osteoporosis, at least in the patient group studied." (PMID 31278293, 2019). "Cathepsin Z mRNA in human peripheral blood mononuclear cells was significantly differentially-expressed among non-osteoporotic controls, osteopenia and osteoporosis patients (p < 0.0001) and in female osteoporosis patients over the age of 50 years (P = 0.0016)." (PMID 31278293, 2019). "However, in patients with osteopenia and osteoporosis, the cathepsin Z mRNA levels were not significantly different between those with and those without inflammatory disorders (P = 0.774)." (PMID 31278293, 2019).
pancreatic cancer (3 papers, 2022 to 2025). "Extracellular cathepsin Z has been implicated in tumor metastasis and proliferation through its integrin-binding domain in a pancreatic tumor model." (PMID 34864055, 2022). "In addition, within the 20q arm, the gene CTSZ was the most frequently amplified gene in pancreatic cancer." (PMID 36289850, 2022).
Sepsis (3 papers, 2018 to 2024). Sepsis is defined as life-threatening organ dysfunction caused by a dysregulated host response to infection. "CTSZ expression was significantly higher in patients with CCI compared to patients who rapidly recovered after sepsis, and has been previously identified as a septic marker in mice." (PMID 38720891, 2024). "Increased expression and altered localization of CTSZ were also observed in hepatocytes at end stages of other cholestatic liver diseases, including Alagille syndrome, obstructive jaundice, and sepsis." (PMID 34440927, 2021). "Fifth, increased expression and altered localization of cathepsin Z were also observed in hepatocytes at the end stage of other cholestatic liver diseases, including Alagille syndrome, obstructive jaundice, and sepsis." (PMID 30087368, 2018). "Similar altered expression of cathepsin Z was observed in end-stage of other cholestatic liver diseases including sepsis, obstructive jaundice, and Alagille syndrome." (PMID 30087368, 2018). "Cathepsin Z protein expression was markedly increased in hepatocytes at the end stage of sepsis, Alagille syndrome, and obstructive jaundice as compared to NL." (PMID 30087368, 2018). "In addition, the cathepsin Z was translocated from the bile canaliculus region of hepatocytes to the cytoplasm, particular in sepsis and Alagille syndrome and immunofluorescence staining showed that cathepsin Z was no longer colocalized with LAMP1 in all three diseases." (PMID 30087368, 2018).
Cholestatic liver disease (2 papers, 2018 to 2021). "Our results indicate that altered expression and localization of cathepsin Z is a phenomenon particular to cholestatic liver diseases such as PBC and is implicated in the progression of PBC." (PMID 30087368, 2018). "Our results indicate that altered expression and localization of cathepsin Z in hepatocytes are characteristic features of PBC and other cholestatic liver diseases, and are implicated in the progression of PBC." (PMID 30087368, 2018). "Finally, in contrast to PBC and other cholestatic liver diseases, cathepsin Z was not increased in sea and liver tissues of CHC." (PMID 30087368, 2018).
esophageal cancer (2 papers, 2024 to 2025). A primary or metastatic malignant neoplasm involving the esophagus. "Among them, the genes CTSZ, CTSC, DAD, COLEC12, ATOX1, etc., in the TUBA1B+Mac-C0 cluster have a causal relationship with esophageal cancer." (PMID 38434988, 2024). "The Mendelian randomization results indicate a causal relationship between genes such as CTSZ, CTSC, DAD1, COLEC12, ATOX1 in the TUBA1B+Mac-C0 cluster and the occurrence of esophageal cancer." (PMID 38434988, 2024). "Genes causally associated with the occurrence of esophageal cancer are identified within the AGG cluster, including CTSZ, CTSC, DAD, COLEC12, ATOX1, etc., offering new evidence for clinical immune therapy." (PMID 38434988, 2024). "Mendelian randomization analysis revealed a causal relationship between genes such as CTSZ, CTSC, DAD, COLEC12, ATOX1, within the AGG cluster, and the onset of esophageal cancer." (PMID 38434988, 2024).
lung carcinoma (2 papers, 2021 to 2022). "CTSZ protein levels in serum were significantly higher for lung cancer than in the healthy control subjects and presented short overall survival rates." (PMID 34378678, 2021).
melanoma (2 papers, 2011 to 2022). A malignant, usually aggressive tumor composed of atypical, neoplastic melanocytes. "A cDNA microarray study also illustrated that CTSZ was one of those upregulated genes related with melanoma malignancy." (PMID 21966391, 2011).
neuroblastoma (2 papers, 2022 to 2024). Neuroblastoma (NB) is the most common solid, extracranial childhood tumor. "To address a possible common role of highly expressed and functional important CTS proteases, we generated CTSB-, CTSD-, CTSL-, and CTSBDL-triple deficient (KO) human neuroblastoma-derived SH-SY5Y cells and CTSB-, CTSD-, CTSL-, CTSZ and CTSBDLZ-quadruple deficient (KO) HeLa cells." (PMID 38775843, 2024).
obstructive jaundice (2 papers, 2018 to 2021). A finding indicating increased bilirubin levels in the blood and urine, due to intrahepatic or extrahepatic obstruction of the biliary system. "On the other hand, serum cathepsin Z levels were significantly lower in CHC than in PBC and obstructive jaundice." (PMID 30087368, 2018).
prostate tumors (2 papers, 2021 to 2025). "Future functional studies targeting these pathways could provide mechanistic insights into how CTSZ promotes malignant transformation in genomically unstable prostate tumors." (PMID 40568593, 2025).
silicosis (2 papers, 2022 to 2025). Silicosis is a respiratory disease caused by breathing in (inhaling) silica dust. "Therefore, it is possible that cathepsin Z’s contribution to inflammation in the mouse model of silicosis may involve both IL-1β generation and other inflammatory processes." (PMID 34864055, 2022). "Furthermore, because silicosis is mediated in part by the NLRP3 inflammasome, these findings are consistent with the involvement of cathepsin Z in the activation of the NLRP3 inflammasome." (PMID 34864055, 2022). "Given the observation that the absence of cathepsin Z does not completely prevent inflammation from occurring in our silicosis model, it is possible that there are NLRP3-independent processes contributing to the development of silicosis, as has previously been reported." (PMID 34864055, 2022).
thyroid cancer (2 papers, 2025). "In studies related to thyroid cancer, the role of cathepsins in its development and progression is not yet fully understood; particularly, the functions of cathepsin Z in papillary thyroid carcinoma have not been definitively determined." (PMID 39791166, 2025).
amyloid (1 paper, 2018). "Taken together, our results implicate systemic LPS administration in ameliorating amyloid pathology in early-to-mid stage disease in the APPSWE/PS1ΔE9 mouse and attract attention to the potential disease involvement of cathepsin Z expressed in CNS myeloid cells in AD." (PMID 30459560, 2018).
cervical cancer (1 paper, 2019). A primary or metastatic malignant neoplasm involving the cervix. "The RNAseq data also revealed significantly poorer survival of patients with cervical cancer when related to high CTSB and CTSZ expression." (PMID 31748500, 2019).
cholestasis (1 paper, 2018). Impairment of the bile flow caused by obstruction within the liver, or outside the liver in the bile duct system. "Thus, increased expression and altered localization of cathepsin Z are not only a result of cholestasis, but may also be a cause of hepatocyte cell death, leading to the progression of PBC." (PMID 30087368, 2018).
Cirrhosis (1 paper, 2011). A chronic disorder of the liver in which liver tissue becomes scarred and is partially replaced by regenerative nodules and fibrotic tissue resulting in loss of liver function. "The correlation between CTSZ upregulation and clinical-pathological features including gender, age, HBsAg, serum AFP, tumor size, cirrhosis, adjacent organs invasion, reccurrence or metastasis, tumor encapsulation and tumor stage were studied." (PMID 21966391, 2011).
clear cell renal cell carcinoma (1 paper, 2025). "Fan Zhang found that concentrations of CTSZ were linked to the outcomes of individuals with clear cell renal cell carcinoma (ccRCC) (hazard ratio = 1.5, P = 0.007), where elevated CTSZ levels corresponded to worse prognoses during anti-PD-1 monotherapy." (PMID 39791166, 2025).
diabetes (1 paper, 2025). "The changes seen for DKK1, cathepsin A, cathepsin S, cathepsin Z, and FGF23 that potentially favor a bone resorptive state may contribute to the resorptive effects of RANKL in diabetes." (PMID 41373586, 2025).
epilepsy (1 paper, 2023). A brain disorder characterized by episodes of abnormally increased neuronal discharge resulting in transient episodes of sensory or motor neurological dysfunction, or psychic dysfunction. "Validation of epilepsy and stress cardiomyopathy co-expressed genes at the single-cell level revealed that ALDOA, CTSZ, ERBBS, HLA-DMB and other genes were validated as double disease significant co-expression genes." (PMID 36776884, 2023). "No studies in the same field have confirmed the role of SPOCK2, CTSZ and HLA-DMB in epilepsy or stress cardiomyopathy." (PMID 36776884, 2023).
Gastric Metaplasia (1 paper, 2017). Intestinal metaplasia of the gastric mucosa is an intermediate precancerous gastric lesion in the gastric cancer cascade from chronic gastritis and atrophy to dysplasia and adenocarcinoma. "Cathepsin Z has been shown to be upregulated in human gastric mucosa that is chronically infected with Helicobacter pylori, and to contribute to chronic inflammation and the development of gastric metaplasia in a mouse model of Helicobacter-induced gastritis." (PMID 28486971, 2017).
Granuloma (1 paper, 2025). A compact, organized collection of mature mononuclear phagocytes, which may be but is not necessarily accompanied by accessory features such as necrosis. "We positively identified CTSZ within granuloma-associated CD68+ macrophages from Mtb-infected lung tissue." (PMID 40924769, 2025). "Finally, we examine patient-derived TB granulomas and report CTSZ localization within granuloma-associated macrophages, placing human CTSZ at the host–pathogen interface." (PMID 40924769, 2025). "To confirm whether elevated CTSZ transcription corresponded with elevated CTSZ protein levels in patient tissue samples, we performed immunostaining on granulomas biopsied from the lungs of patients with culture-confirmed TB." (PMID 40924769, 2025).
hypoglycaemia (1 paper, 2025). "Following hypoglycemia, transient changes from baseline occurred in DKK1, cathepsin A, cathepsin G, cathepsin H, cathepsin S, cathepsin Z, parathyroid hormone (PTH), Sphingosine kinase 1 and 2 (SPK1/2), and interleukin-1 beta (IL1 beta) over the post-hypoglycaemia time course." (PMID 41373586, 2025).
in situ breast cancer (1 paper, 2025). "Our findings indicate that specific cathepsins, such as cathepsins E and F, are associated with an increased risk of malignant and in situ breast cancer, while cathepsin Z appears to have a protective effect against in situ breast cancer." (PMID 39944834, 2025). "ADCY3 and PELATON are risk factors for both cathepsin Z and in situ breast cancer." (PMID 39944834, 2025). "It was found that cathepsins E and F increased the risk of malignant breast cancer and in situ breast cancer, respectively, whereas cathepsin Z had a protective effect against in situ breast cancer." (PMID 39944834, 2025). "Additionally, cathepsin Z has a protective effect against in situ breast cancer (IVW: p = 0.017, OR = 0.846, 95% CI = 0.737-0.971)." (PMID 39944834, 2025). "Furthermore, cathepsin Z was found to have a potential protective effect against in situ breast cancer (IVW: p = 0.017, OR = 0.846, 95% CI = 0.737-0.971)." (PMID 39944834, 2025). "However, when the direction of effect is opposite (as seen for some genes and cathepsins, such as CTSF and CTSZ in in situ breast cancer), this indicates the possibility of compensatory mechanisms, where other factors might counterbalance the effect of gene expression or cathepsins." (PMID 39944834, 2025). "Cathepsin Z can mediate the effects of PRX, CRY2, ADCY3, and PELATON on in situ breast cancer." (PMID 39944834, 2025).
inflammatory breast carcinoma (1 paper, 2021). An advanced, invasive breast adenocarcinoma characterized by the presence of distinct changes in the overlying skin. "It is known that CTSZ protein levels in the serum of patients with inflammatory breast cancer are lower than in healthy subjects." (PMID 34378678, 2021).
influenza (1 paper, 2022). An acute viral infection of the respiratory tract, occurring in isolated cases, in epidemics, or in pandemics; it is caused by serologically different strains of viruses (influenzaviruses) designated A, B, and C, has a 3-day incubation period, and usually lasts for 3 to 10 days. "Notably, a number of proteins lacking a signal peptide and not annotated as ‘secreted’ elsewhere were overrepresented in the influenza stimulated group, including the proteases cathepsin c, cathepsin z, legumain, and the transcription factor IRF8." (PMID 35401570, 2022).
iron deficiency (1 paper, 2021). "Furthermore, iron deficiency has been shown to inhibit expression not only of CTSZ, the gene for the cysteine protease cathepsin Z, which has been associated with malignancy and inflammation, but also of CASP5, the gene for the cysteine peptide Caspase 5, which is involved in cellular apoptosis." (PMID 33777027, 2021).
Macrothrombocytopenia (1 paper, 2015). "Mutations in these genes have been associated with macrothrombocytopenia (TUBB1,), mitochondrial complex V (ATP synthase) deficiency nuclear type (ATP5E,) or even tumour metastasis (CTSZ,)." (PMID 25710380, 2015).
meningitis (1 paper, 2018). A disorder characterized by acute inflammation of the meninges of the brain and/or spinal cord. "There are no reports on the role of CTSZ and CTSL1 in SS meningitis." (PMID 29479521, 2018).
non-small cell lung carcinoma (1 paper, 2022). A group of at least three distinct histological types of lung cancer, including non-small cell squamous cell carcinoma, adenocarcinoma, and large cell carcinoma. "Cathepsin Z has also been shown to physically interact with the β3 integrin in non small cell lung cancer cells." (PMID 34864055, 2022).
oral cancer (1 paper, 2021). "Specifically, we assessed the expressions of cathepsin L (CTSL), cathepsin S (CTSS), cathepsin A (CTSA), and cathepsin Z (CTSZ) in platyphyllenone-treated oral cancer cells." (PMID 34065077, 2021).
osteoarthritis (1 paper, 2021). A noninflammatory degenerative joint disease occurring chiefly in older persons, characterized by degeneration of the articular cartilage, hypertrophy of bone at the margins and changes in the synovial membrane. "Furthermore, inflammation modulators (such as CSTB, CTSD, and CTSZ), which have been reported to contribute to osteoarthritis, were more highly expressed in the medial than lateral meniscus." (PMID 34360947, 2021).
papillary thyroid carcinoma (1 paper, 2025). "There is a paucity of research on the intrinsic relationship between cathepsin Z and papillary thyroid carcinoma." (PMID 39791166, 2025).
periodontitis (1 paper, 2024). An acute or chronic inflammatory process that affects the tissues that surround and support the teeth. "Spatial transcriptomics revealed significant upregulation of ACTB, GSTO1, RAB1B, HBB, DMKN, and CTSZ in basal epithelial cells during periodontitis." (PMID 39769019, 2024).